IL33 (interleukin 33)
Diseases named in the same sentence as IL33 in open-access papers (continued):
Sharing a sentence is not in itself a finding about the gene and the disease.
tumor (continued). "In addition, exogenous IL-33 enhanced the immunostaining intensity and mRNA levels of S100A9, which induced epithelial-mesenchymal transition and led to tumour occurrence." (PMID 33308251, 2020). "Accumulating studies also demonstrated that the anti-tumor effects of IL-33 mediated by non-tumor cells." (PMID 32003751, 2020). "In mice with colorectal cancer (CRC), tumour-infiltrating Tregs preferentially upregulated ST2, and IL-33/ST2 signalling positively correlated with tumour burden, which favours their accumulation in the TME and concomitantly restrains the frequencies of effector CD8+ T cells." (PMID 32680511, 2020). "shRNA-mediated knockdown of sST2 expression in the cells suppressed orthotopic tumor growth, which was partially recovered by overexpression of shRNA-resistant sST2 mRNA but was not evident in IL-33 knockout mice." (PMID 32340025, 2020). "To investigate the influence of exogenous IL-33 on pro-inflammatory factors, such as IL-6, IL-1β, and tumour necrosis factor (TNF)-α, we measured their mRNA expressions, which are known to stimulate tumour proliferation and angiogenesis." (PMID 33308251, 2020). "In contrast, we did not observe polarization of CD11a/CD18 to the EO-tumor cell synapses in either IL-33-activated or control IL-5 EO." (PMID 31717819, 2019). "Although this study suggests an important antitumor role for ILC2s dependent on IL-33 activation, this role remains to be confirmed in a more physiological tumor setting, where IL-33 is not overexpressed." (PMID 32063901, 2019). "Also, stromal ST2 was decreased in patients with left-sided cancer and LN metastasis and inversely correlated with desmoplasia, suggesting that IL-33/ST2 axis participates in CRC desmoplasia and tumor progression in this subgroup of patients." (PMID 31281317, 2019). "Dependent on the cancer milieu, IL-33 may influence anticancer immunity, stimulating CD8-positive T cells essential for the elimination of tumor cells." (PMID 31652497, 2019). "IL-33 binds to CD8 T cells, leading to tumor cells to escape the recognition of CD8 T cells." (PMID 31186061, 2019). "Of note, when eosinophils were co-cultured with tumor cells, a marked polarization of EPX, ECP, and granzyme-B to the immune synapses was observed selectively in IL-33 EO." (PMID 31717819, 2019). "Although CD11a/CD18 was reported to mediate adhesion and subsequent killing of tumor cells by human eosinophils, this molecule was neither up regulated in IL-33 EO nor polarized to the EO-tumor cell synapses." (PMID 31717819, 2019). "Hence, we analyzed IL-33 and ST2 content in tumor and healthy tissue lysates and plasma from CRC patients." (PMID 31281317, 2019). "IL-33 blockade using the IL-33 neutralizing antibody or the ST2 neutralizing antibody resulted in reduced proliferative survival of NSCLC cells and diminished regulatory T cells (Treg) cells in tumor tissues." (PMID 31130612, 2019). "As opposed to controls, tumor tissues from IL-33-treated mice displayed the substantial presence of degranulating tumor-infiltrating eosinophils within tumor necrotic areas, as revealed by co-expression of Siglec-F with EPX and granzyme-B." (PMID 31717819, 2019). "IL-33 was found to be co-expressed with this lnc-CAF, resulting in elevation in the expression of CAF markers, conversion of the normal fibroblast phenotype to stromal carcinoma-related fibroblasts and enhanced tumor growth." (PMID 31231372, 2019). "In addition, we found that the IL-33/ST2 pathway suppresses IL-17 production and thereby modifies the inflammatory signals within the tumor microenvironment." (PMID 31165767, 2019). "In this setting, ILC2s partially antagonized the IL-33 dependent, NK cell-mediated anti-tumor response, as evidenced by cell depleting experiments in which the lack of ILC2 CD73+ cells led to enhanced NK cell activity and better tumor control." (PMID 31849977, 2019).
tumor (continued). "Here, we confirm this concept and provide, for the first time, a mechanism induced by IL-33 and mediated by the integrin CD11b/CD18 that triggers granule convergence to immune cell synapses in eosinophil-tumor cell conjugates, degranulation, and tumor toxicity." (PMID 31717819, 2019). "It was then hypothesized that IL-33 promotes RCC cell proliferation and chemotherapy resistance via its receptor ST2 and the JNK signaling activation in tumor cells." (PMID 30769901, 2019). "In ID8hPON2 cells, the expression profile of many genes known to regulate tumor growth including BRCA1, cyclin and cyclin-dependent kinase 20, PTK2, Hypoxia-upregulated protein 1, p21-activated kinase 3, IL-18, IL-33, IGF-1, IGFBP2 and RNA-binding protein 9, were identified." (PMID 29531225, 2018). "In this study, we found that there were positive correlations between the expression of ST2 and FOXP3, CD11B, and CD33, indicating that the IL-33/ST2 axis may also regulate the function of Tregs and MDSCs in the tumor microenvironment of STS." (PMID 29896199, 2018). "ILC2s participate in immune surveillance against CTCs, since in transplantable murine models they are recruited to the primary tumor in an IL-33-reliant manner and mediate CTL activation together with DCs, hence producing a decrease in tumor growth, CTCs (evaluated by FACS), and metastasis." (PMID 30200242, 2018). "Similarly, IL-33 increased IFN-γ by CD8(+) T and NK cells in tumor tissues, thereby inducing the microenvironment accessible to tumor eradication." (PMID 30619376, 2018). "Indeed, IL-33 expression in several cancers affects the number of CD8+ T cells and NK cells in tumor tissues and the production of IFN-γ/TNF-α, thereby favoring tumor eradication through tumor cell cytolysis." (PMID 30416507, 2018). "Taken together, these results indicate that the IL-33/ST2 axis may regulate the immune function of Th1, CD8+ T cells, and memory T cells, as well as Tregs and MDSCs in the tumor microenvironment of STS." (PMID 29896199, 2018). "The frequency of ILC2s isolated from lymph nodes of WT animals bearing IL-33-expressing tumours (i.e, TC-1 or A9+IL-33) was significantly increased over animals bearing tumours not expressing IL-33 (i.e. A9 alone)." (PMID 29440650, 2018). "Thus, our results demonstrate the important role of IL-33 in dectin-1-activated DC-induced Th9 cell differentiation and antitumor efficacy, and suggest that the combination of dectin-1-activated DCs and IL-33 may present a new effective modality of DC-based vaccines in tumor immunotherapy." (PMID 30108595, 2018). "It has been proposed that IL-33 stimulates cell migration through the expression of matrix metalloproteinases (MMP2/MMP9) via the ST2/ NF-κB pathway, thereby promoting cell invasion and tumor growth." (PMID 30483263, 2018). "B16-OVA tumor-bearing OT-II mice were immunized with OT-II OVA peptide-pulsed BMDCs or CurDCs with or without addition of IL-33." (PMID 30108595, 2018). "Next, we assessed the level of ILC2 infiltration into primary (TC1) or metastatic (A9) tumours, with or without IL-33 complementation." (PMID 29440650, 2018). "To determine how IL-33/ST2 might promote SCC development, we next characterized the immune cell infiltrate of the tumor microenvironment." (PMID 30112116, 2018). "Thus, the IL-33/ILC2 axis is a missing link between the adaptive and innate immune responses during tumour development." (PMID 29440650, 2018). "In a mouse model of CCA, administration of IL-33 in combination with ectopic expression of constitutively active AKT (myr-AKT) and Yes-activated protein (YAP) oncogenes induced tumor development in 72% of mice as compared to 20% in the absence of IL-33." (PMID 30205617, 2018). "Accordingly, the frequency of ILC2s isolated from resected IL-33 expressing tumours from mice transplanted with WT BM was consistently higher, when compared to tumours not expressing IL-33." (PMID 29440650, 2018).
tumor (continued). "Similarly, experimental studies in a murine model showed that overexpression of IL-33 promoted the expansion of ST2+Tregs, increased Th2 cytokine milieu, and induced M2 macrophages in the gut, thereby increasing tumor development." (PMID 30405626, 2018). "In addition, it has been shown that the IL-33/ST2 interaction drives the polarization of naïve T cells towards a Th2 phenotype and that blocking this pathway amplifies anti-tumor Th1-immune responses." (PMID 30112116, 2018). "The ELISA assay indicated that IL-6 knock-out could down-regulate IL-33 and VEGF-A secretion, which may restore M1 phenotype and inhibit tumor angiogenesis, growth, and recurrence." (PMID 29100435, 2017). "Mechanistically, IL-33 blockade suppresses outgrowth of NSCLC cells, abrogates polarization of M2 TAMs and reduces accumulation of Treg cells, shaping immune surveillance in tumor microenvironments." (PMID 28978138, 2017). "Previous work showed that higher expression of total IL-33 and ST2 correlates with CRC progression and metastasis, with inhibition of IL-33 in CRC cells resulting in reduced cell migration, colony formation and tumor growth in vitro, and smaller tumors in vivo." (PMID 28715472, 2017). "Immunohistochemical staining of these proteins in biopsies from human OvCa peritoneal implants showed mesothelial‐derived (calretinin‐positive) spindle‐like cells in the stroma tissue surrounding tumour nodules, overlapping with areas with marked staining for MMP1, IL‐33, EGR1, TSP1, and GREM1." (PMID 28247413, 2017). "We show here that the expression of IL-33 is higher in the epithelium of moderate- and poorly-differentiated CRC than in well-differentiated tumors suggesting a positive correlation of IL-33 expression in the epithelium and tumor grade." (PMID 28710436, 2017). "On the other hand, it was also reported that the IL‐33/ST2L signaling axis exhibits an antitumor function 32, 33, suggesting that the functional direction of ST2 gene products seems to depend on the environmental conditions such as the tumor cell type." (PMID 28174694, 2017). "Tumour ulcerations (stage 4–5) with bleeding of adjacent tissues were detected for some cases in the group injected with metastatic A9 cells, but this was not seen in animals injected with primary TC1 or metastatic A9+IL-33 tumours." (PMID 27619158, 2016). "On the basis of these observations, we concluded that some but not all P29 cells in the tumours express IL-33." (PMID 26775708, 2016). "High expression of IL-33 in vivo tumour tissues but not in vitro cultured Panc02 tumour cells indicated that host cellular components in tumour tissues contributed to IL-33 expression." (PMID 27150562, 2016). "In contrast, CD31+ vascular endothelial cells did not significantly contribute to PDGF-BB-induced IL-33 expression in tumours since IL-33 levels in PDGF-BB positive population was not increased." (PMID 27150562, 2016). "Thus, it is likely that blocking of IL-33/IL-33R signaling on its own and by attenuating VEGF expression in tumor cells and subsequent neoangiogenesis promote tumor necrosis." (PMID 26919112, 2016). "Furthermore, IL-33 selected for the ST2L-positive, oncosis-resistant high-metastatic cells under conditions mimicking the tumour microenvironment." (PMID 26775708, 2016). "As expected, P29 cells formed smaller primary tumours with an increase in necrotic regions in B6 mice than in IL-33−/− mice, irrespective of the similar vessel density." (PMID 26775708, 2016). "Both, IL-33 and IL-33R expression correlated with VEGF expression in tumor cells." (PMID 26919112, 2016). "In contrast, the treatment of tumour-bearing mice with the control liposome did not significantly affect macrophage numbers in IL-33 tumours as compared with controls." (PMID 27150562, 2016). "Unexpectedly, P29 tumours in IL-33−/− mice did express IL-33 protein irrespective of that P29 cells hardly express IL-33 in vitro, although the amount was lower than that in B6 mice." (PMID 26775708, 2016).
tumor (continued). "By using the median IHS value of 3 as a cut-off value, 70 tumor tissues from Group B were divided into TTP-positive (n = 26, IHS > 3) subgroup, TTP-negative (n = 44, IHS ≤ 3) subgroup, IL-33-positive (n = 50, IHS > 3) subgroup, IL-33-negative (n = 20, IHS ≤ 3) subgroup." (PMID 27074834, 2016). "Our data suggest that IL-33 does not directly affect the proliferation of tumor cells, but rather decreases the barrier function of the intestine." (PMID 27148488, 2016). "In disaggregated tumour tissues, FACS analysis indicated CD8+ T cell content was lower in metastatic A9 tumours than in either the primary (TC1) or the modified metastatic A9+IL-33 tumours." (PMID 27619158, 2016). "Moreover, expression levels of IL33 and ST2 correlate with tumor grade and inferior survival of glioblastoma patients." (PMID 28119694, 2016). "Whether IL-33, sST2, and VEGF play a role in the promotion or eradication of tumors, the tumor immunoregulatory effect on them is weakened along with tumor disappearance." (PMID 24636276, 2014). "Deletion of IL-33/ST2 function enhances cytotoxicity of NK cells and increases levels of TNF-α, IFN-γ, and IL-17, and systemic pro-inflammatory cytokines, leading to attenuated tumor growth." (PMID 24778632, 2014). "Regarding mechanism, IL-33 activates the p38- GATA binding protein 3 (GATA3) signaling pathway to induce M2 polarization of macrophages, promote Th2 cells and ILC2 to secrete tumor-promoting cytokines, mainly IL-4, IL-5, and IL-13, thereby playing a role in promoting tumor development." (PMID 39925809, 2025). "Notably, restricting IL-33 and eradicating the pancreatic intratumoral mycobiome using antifungal treatments significantly reduced the infiltration by Th2 and ILC2 cells and increased the survival rates of the tumor-bearing mice." (PMID 39854185, 2025). "To further enhance the anti-tumor efficacy of Xcl1-E6E7, we explored the immunization of mice with the Xcl1-E6E7 plasmid in combination with several plasmids expressing interleukins known to stimulate T cell proliferation and memory formation, including IL-7, IL-9, IL-21, and IL-33." (PMID 39852828, 2025). "In addition, in in vitro human glioma cell line experiments, IL-33 stimulated the secretion of matrix metallopeptidase 2 (MMP-2) and MMP-9 through the ST2-NF-κB pathway, thereby increasing the migration and invasion of tumor cells." (PMID 39925809, 2025). "Additionally, IL-33 from the TME could further upregulate IL-33 and ST2 expression within the tumor cells themselves, forming its own positive feedback regulation." (PMID 40216748, 2025). "We previously demonstrated in a Lewis lung carcinoma (3LL) model that IL‐33 induces the death of ST2L‐positive weak metastatic cells but not of ST2L‐negative highly metastatic cells, suggesting the selection of highly metastatic cells within the tumor microenvironment." (PMID 40751595, 2025). "Moreover, PD-1 mAb combined with either IL-33 or DAC alone failed to synergistically reduce tumor growth." (PMID 40317004, 2025). "Organ metastasis presented the lowest mean IL-33 levels (32.6 pg/mL), reinforcing the notion that IL-33 may play a more prominent role in local invasion and tumor progression rather than in systemic dissemination." (PMID 40725273, 2025). "Indeed, we observed IL-33 expression in the tumor cells of human mandibular gingival SCC specimens, but not as strongly as in the nuclei of the vascular endothelium." (PMID 41374934, 2025). "Additionally, a study on a melanoma model observed an IL-33-induced decrease in cancer growth due to the invasion of CD8+ T cells and eosinophils in the TME and found that eosinophils are able to exert a direct cytotoxic action on tumor cells in vitro." (PMID 39766202, 2024). "Therefore, reduced IL-33 expression in metastatic mouse carcinomas simultaneously decreases both the MHC-I expression and the functional activities of ILC2s and provides a previously undescribed mechanism of immune escape for tumour cells." (PMID 38172434, 2024).
tumor (continued). "This study additionally focused on the dual role of IL-33 in antitumor activity and identified a critical signaling pathway, p38-GATA3, which promoted the M2 polarization of macrophages and simultaneously fostered tumor progression and resolution of inflammation." (PMID 38238529, 2024). "Additionally, IL-33 facilitates EMT, tumor invasion, and metastasis by binding to ST2 on BC cells." (PMID 39609700, 2024). "The context-dependent discrepancies of the IL33 effect on tumor growth may depend on specific recruitments of non-malignant immune cells to the tumor varying in different cancer subtypes." (PMID 38942797, 2024). "Taken together, these data indicate that IL-33 can drive the recruitment and activation of immunologic effector cells and promote the expression of anti-tumor inflammatory cytokines, which reprogram the immunosuppressive TIME into immunoactivated state and inhibit tumor progression and metastasis." (PMID 38238529, 2024). "Furthermore, a cytokine array analysis showed increased Il33 and Cst3 expression in both tumor and serum from KPC-Cdh11+/+ mice compared to KPC-Cdh11+/- mice, while Il11 was highly enriched in KPC-Cdh11+/+ serum alone and Ccl11 was enriched in tumor alone." (PMID 37954069, 2023). "The results showed that the serum level of IL-33 was positively correlated with tumor stage (SMD = 0.936, 95% CI = 0.555–1.317, p < 0.000) and vascular invasion (SMD = 0.601, 95% CI = 0.387–0.815, p < 0.000), which was consistent with the results of the IL-33 tissue level." (PMID 37507682, 2023). "Importantly, removing the PD-1 ectodomain from the PD-1–IgG4 decoy neither impacted tumor control by IL-2v/IL-33-transduced OT1 cells nor impaired the accumulation of PD-1+Gzmc+TCF1neg OT1 TILs." (PMID 37081150, 2023). "However, we did not detect TGF-β+ FcεRIα+ ST2+ macrophages or IL-33 expression from the tumor in our IL-33-treated TB mice (data not shown), probably due to the different source of IL-33, that is, exogenous IL-33, in this study." (PMID 37246159, 2023). "We next examined T-cell immunity in the IL-33- and GM-CSF-treated TB mice and found that the frequency of effector CD8+ cells in the spleen and CTL activity in tumor-infiltrating lymphocytes (TILs) increased significantly in the IL-33-treated mice but not the GM-CSF-treated mice." (PMID 37246159, 2023). "Exogenously administered IL-33 increased the expression of alarmins, Th2 chemokines (CCL17 and CCL22), CD8 + T cell chemokines (CXCL10, CX3CL1), eosinophil chemokines (CCL11, CCL13, CCL24), as well as Th2-related cytokines (IL-4, IL-13) and Th1 effector molecules (granzyme B) in the primary tumor." (PMID 37587450, 2023). "IL-33-mediated tumor suppression did not occur in Batf3−/− mice." (PMID 37246159, 2023). "However, we did not assess the expression level of IL-33 before and after 5-FU treatment owing to the unavailability of tumor tissues from patients with CRC after 5-FU-based chemotherapy." (PMID 37056569, 2023). "Altogether our findings suggest that the presence of SCF and IL-33 in CRC tissues favor the accumulation of a connective tissue-like MC phenotype which through the production of IL-6 and TNF-α contribute to the establishment of an inflammatory tumor microenvironment." (PMID 37730723, 2023). "However, IL-33 may stimulate hILC2s to produce the immunosuppressive ectoenzyme CD73, thereby promoting tumor growth." (PMID 36246629, 2022). "IL-33, as a candidate for cytokine therapies, can effectively enhance Sema4A expression and stimulate anti-tumoral cells including NK and CD8+ T cells, while the mechanism of IL-33 on anti-tumor effects remains unclear." (PMID 35155237, 2022). "Similarly, human CRC IL33 and ST2 expression varies according to tumour stage." (PMID 36263033, 2022).